AOPEP (aminopeptidase O (putative))
Description:
Aminopeptidase which catalyzes the hydrolysis of amino acid residues from the N-terminus of peptide or protein substrates.
Synonyms: AP-O; C9orf3; ONPEP; C90RF3; FLJ14675; APO; DYT31
Tractability: Small molecule: a drug acting on it is in phase 2 or 3 trials. PROTAC: ubiquitination databases record sites on it.
Gene: Protein-coding gene on chromosome 9 (94,726,604 to 95,151,793, forward strand). Ensembl gene ENSG00000148120.
Subcellular location: Nucleus, nucleolus; Cytoplasm (Isoform 3)
Subcellular location (Human Protein Atlas): Cell Junctions
Gene Ontology:
Molecular function: metalloaminopeptidase activity; metallopeptidase activity; zinc ion binding
Cellular component: cytoplasm; nucleolus
Genetic constraint (gnomAD): Loss-of-function variants: 55 observed, 70.36 expected, observed/expected ratio (o/e) 0.78, 90% interval 0.63 to 0.98. The upper end of that interval is the gene's LOEUF score, 0.98, which puts it in group 4 of 6, group 1 being the genes least tolerant of losing a copy. Missense variants: 829 observed, 876.12 expected, observed/expected ratio (o/e) 0.95, 90% interval 0.89 to 1. Synonymous variants: 288 observed, 311.45 expected, observed/expected ratio (o/e) 0.92, 90% interval 0.84 to 1.02.
Homologues: Orthologues: chimpanzee AOPEP (99% identical), macaque AOPEP (90% identical), rabbit AOPEP (84% identical), dog AOPEP (81% identical), rat Aopep (77% identical), mouse Aopep (77% identical), guinea pig AOPEP (71% identical), tropical clawed frog aopep (60% identical), Caenorhabditis elegans F49B2.6 (12% identical), Drosophila melanogaster CG31445 (12% identical), Caenorhabditis elegans Y42A5A.1 (11% identical), Drosophila melanogaster CG46339 (11% identical), and 10 more. Paralogues in human: RNPEP (20% identical), RNPEPL1 (20% identical), LTA4H (17% identical), TRHDE (16% identical), ANPEP (14% identical), ERAP2 (13% identical), ERAP1 (13% identical), LNPEP (13% identical), LVRN (12% identical), ENPEP (11% identical), NPEPPS (11% identical).
Diseases named in the same sentence as AOPEP in open-access papers:
AOPEP is named in the same sentence as 48 diseases in open-access papers, as found by Europe PMC text mining. Sharing a sentence is not in itself a finding about the gene and the disease. The quoted sentences say what the papers report.
Dystonia (5 papers, 2024 to 2026). An abnormally increased muscular tone that causes fixed abnormal postures. "Biallelic LoF variants in another regulator of protein turnover, AOPEP (aminopeptidase O), have been implicated in isolated dystonia." (PMID 41518464, 2026). "The analysis of oscillatory behavior across all frequency bands revealed that PANK2 and AOPEP neurons oscillate less (≤ 59.3%) than neurons of remaining dystonia‐causing genes." (PMID 39887724, 2025). "In addition to these 45 individuals, we identified ten carriers of single heterozygous pathogenic variants in recessively inherited dystonia genes, including AOPEP (n=5), SPR (n=4), and HPCA (n=1)." (PMID 40672488, 2025). "In addition, we identified a homozygous truncating variant in AOPEP (C9orf3) gene in a multigeneration family (DYS-98) with two affected individuals presenting with early adulthood-onset isolated dystonia." (PMID 38458754, 2024). "Recent discoveries have expanded the genetic landscape of dystonia, identifying novel contributors such as AOPEP, VPS11, VPS16, and EIF2AK2." (PMID 40584247, 2025).
Hypertension (2 papers, 2020 to 2024). The presence of chronic increased pressure in the systemic arterial system. "Two of the recurrent AF genes also code for functions directly or indirectly linked to AF (CASQ2 and GOSR2), and some genes indicate a possible indirect link related to comorbidities, e.g., hypertension or malignancy (PPFIA4, USP34, WIPF1, SPATS2L, CAND2, and AOPEP)." (PMID 38725839, 2024).
Atrophy (1 paper, 2024). Any weakening or degeneration, especially through lack of use. "Additionally, research has identified pathogenic genes related to muscle atrophy, such as AOPEP, suggesting a potential novel approach for patients with cachexia to improve muscle symptoms by altering the composition of gut microbiota." (PMID 38384268, 2024).
muscle atrophy (1 paper, 2024). The loss of muscle tissue due to inactivity or disease. "Mutations in AOPEP were found to be associated with muscle atrophy and impaired muscle tone in a large-scale multicenter study." (PMID 38384268, 2024).
sarcopenia (1 paper, 2024). Progressive decline in muscle mass due to aging which results in decreased functional capacity of muscles. "Interventions such as drug treatments or microbiota transplantation, aimed at elevating Lachnospiraceae abundance and AOPEP inhibition, synergistically improve sarcopenia in the elderly, thereby enhancing the overall quality of life for older individuals." (PMID 38384268, 2024). "Therefore, interventions such as drug treatments or microbiota transplantation aimed at augmenting the abundance of Lachnospiraceae and AOPEP inhibitor synergistically improve sarcopenia in the elderly, thereby enhancing the overall quality of life for older individuals." (PMID 38384268, 2024).
virus infection (1 paper, 2021). "Human miR-24-1 along with miR-23b and miR-27b, is embedded in the 3’UTR of AOPEP mRNA; all were induced in HT1080 cells by virus infection." (PMID 34591940, 2021).
cancer (2 papers, 2020). A tumor composed of atypical neoplastic, often pleomorphic cells that invade other tissues. "However, the function of AOPEP in cancer development has not been elucidated." (PMID 31936744, 2020).
AOPEP also shares sentences with these, for which no sentence is quoted: atherosclerosis (4 papers); erectile dysfunction (4); prostate carcinoma (3); tumor (3); type 2 diabetes (3); Alzheimer’s dementia (2); Cognitive impairment (2); dementia (2); diabetes (2); familial hypercholesterolemia (2); Alzheimer's disease (1); anthrax (1); asthma (1); atrial fibrillation (1); brain injury (1); Cachexia (1); cardiovascular disorder (1); cervical cancer (1); ciliary dyskinesia (1); ciliopathies (1); colorectal adenocarcinoma (1); coronary artery disease (1); dyslipidemia (1); Hypercholesterolemia (1); Hyperglycemia (1); hypertriglyceridemia (1); infection (1); Infertility (1); Insulin resistance (1); medulloblastoma (1).
A further 11 diseases each share a sentence with AOPEP in 1 paper.